FRMD3 (FERM domain containing 3)
Diseases named in the same sentence as FRMD3 in open-access papers (continued):
Sharing a sentence is not in itself a finding about the gene and the disease.
tumor (14 papers, 2014 to 2025). "On the other side of the spectrum, the most prominent miRNA-dependent regulation of a barely investigated candidate tumor suppressor, FRMD3, is associated with the upregulation of miR-127-3p and miR-129-5p." (PMID 34885022, 2021). "In several cancers, FRMD3 has been reported to inhibit tumor growth and metastasis, highlighting its potential role as a tumor suppressor gene." (PMID 40488817, 2025). "Similar to the results of mRNA levels from the TCGA database, the protein expression levels of CDH2 and FRMD3 were significantly higher in tumor tissues of THCA than in normal tissues." (PMID 35756646, 2022). "Herein, we identified FERM domain-containing protein 3 (FRMD3) as a novel potent BRCA tumor suppressor which is significantly downregulated in BRCA clinical tissue and cell lines, and low FRMD3 expression has been closely associated with progressive BRCA and shortened survival time in BRCA patients." (PMID 36631457, 2023). "Meanwhile, FRMD3 inhibits integrin synthesis by degrading vimentin, resulting in cytoskeletal rearrangement and reduced focal adhesions and affecting the regulation of downstream proteins on tumor cell tumorigenesis, metastasis, and aggressiveness." (PMID 36631457, 2023). "We also showed the correlation between CDH2 and FRMD3 expression and tumor immune infiltration." (PMID 35756646, 2022). "Next, we collected 28 paired clinically fresh THCA of carcinoma and paraneoplastic tissues, and the results showed that the mRNA expression of CDH2 and FRMD3 were significantly increased in tumor tissues compared with the paraneoplastic tissues by qRT-PCR assay." (PMID 35756646, 2022). "GO and KEEG results showed that CDH2 and FRMD3 were strongly associated with immune-related functions, therefore, we considered that CDH2 and FRMD3 may play an important role in the tumor immune microenvironment." (PMID 35756646, 2022). "Then, we determined whether FRMD3 affected tumor cell invasion." (PMID 36631457, 2023). "Moreover, CDH2 and FRMD3 expression were significantly higher in tumor tissues than in normal tissues, while hsa-miR-410-3p, hsa-miR-411-5p and hsa-miR-299-5p were significantly decreased in tumor tissues compared with normal tissues in THCA." (PMID 35756646, 2022). "Given their tumor‐suppressive roles, it is plausible that GALNT12 and FRMD3 contribute to the favorable prognosis observed in MMR‐mutated UTUC." (PMID 40488817, 2025). "In this study, The mRNA and protein expression levels of FRMD3 were significantly elevated in THCA tissues, implying that FRMD3, similar to CDH2, plays a tumor-promoting function in THCA." (PMID 35756646, 2022). "Results confirmed that BLCAP, EML1, FOSL2, ADNP and FRMD3 were deregulated in the same way among the xenografts, FFPE and OCT tumour samples." (PMID 30592148, 2019). "We further verified the expression levels of ADAMTS9, ENTPD1, FRMD3, PRR15, AKAP12 in THCA, and the results of GEPIA database showed that ENTPD1, FRMD3, PRR15 were obviously increased in tumor tissues (n=512) compared with normal tissues (n=337), and the difference was statistically significant." (PMID 35756646, 2022). "FRMD5, similar to FRMD3, has been reported as a FERM and FA domain-containing novel tumor suppressive molecule, which may maintain cell-cell contact and regulate tumor progression." (PMID 29870543, 2018).
cancer (7 papers, 2014 to 2025). A tumor composed of atypical neoplastic, often pleomorphic cells that invade other tissues. "Epithelial-mesenchymal transition (EMT) plays a critical role in the invasion and metastasis cascades of cancer; therefore, we first assessed the effects of FRMD3 on the EMT of BRCA cells." (PMID 36631457, 2023). "All these data clearly indicated that FRMD3 played an inhibitory role in BRCA cell migration and invasion, the two processes that are closely associated with cancer metastasis and progression." (PMID 36631457, 2023). "Other studies have concerned with the role of FRMD3 in cancer." (PMID 36631457, 2023). "Rescue experiments indicated that FRMD3 knockdown could weaken the repressive effect of the microRNA-423-5p inhibitor on the proliferation, migration, and invasion of cancer cells." (PMID 35912010, 2022). "Moreover, further comprehensive studies are needed to explore whether FRMD3 is downregulated in other malignant tumors, other than BRCA, and its functional roles." (PMID 36631457, 2023). "FNBP1, FRMD3, IGSF10, IL11RA, and TOX2 have known roles in cancer." (PMID 38398114, 2024). "As for the possible mechanisms of FRMD3 inhibiting BRCA cell proliferation, we examined the activation of typical signaling pathways closely related to cancer growth and progression as well as the expression levels of representative cell cycle regulators in FRMD3 overexpression and knockdown cells." (PMID 36631457, 2023).
metabolic disease (1 paper, 2022). A congenital disorder (due to inherited enzyme abnormality) or acquired (due to failure of a metabolically important organ) disorder resulting from an abnormal metabolic process. "Apart from its role in metabolic diseases, FRMD3 was reported to be focally expressed in hormone dependent tissue, i.e., adult ovary." (PMID 34865205, 2022).
FRMD3 also shares sentences with these, for which no sentence is quoted: acute myeloid leukemia (1 paper); leukemia (1); neuroblastoma (1).